PCNA (proliferating cell nuclear antigen)
Diseases named in the same sentence as PCNA in open-access papers (continued):
Sharing a sentence is not in itself a finding about the gene and the disease.
tumor (continued). "In in vitro cellular assay, γ-tubulin was reported to form a complex with proliferating cell nuclear antigen (PCNA), and a significant correlation in expression of γ-tubulin (TUBG1) with PCNA was reported in tumor cells." (PMID 37466845, 2023). "PCNA expression is reported to be unregulated in cancer cells and has been a biomarker for cell proliferation in tumours." (PMID 37817427, 2023). "In our cellular models, we also observed a significant inhibition of cellular proliferation, particularly after Ref-1 silencing, by evaluating PCNA expression as an index of tumor growth and the cellular motility via the scratch assay." (PMID 37628748, 2023). "This was accompanied by a significant decrease in cell proliferation based on the percentage of PCNA positive cells within the tumor mass." (PMID 37098540, 2023). "As described in the literature, PCNA and Ki-67 localized in the nucleus and showed brownish-yellow staining, and brownish-yellow staining significantly increased during tumor expansion." (PMID 37498338, 2023). "For example, the proliferation index in tumor cells was high (40–50% Ki-67 and PCNA positivity), and staining for ZEB1 was low (although ZEB1 was easily detected in nearby stromal cells with mesenchymal differentiation)." (PMID 37349501, 2023). "The overexpression of PCNA in the cell nucleus is known to correlate with cancer virulence (necessary for tumor survival), DNA replication, DNA repair, chromatin structure maintenance, chromosome segregation, and cell cycle progression." (PMID 37686697, 2023). "Due to its role in cell proliferation, PCNA is deemed as the tumor marker for diagnosis and patient prognosis." (PMID 36776764, 2023). "In comparison with the intermediate-grade and low-grade MECs, the numbers of chymase-positive mast cells and PCNA-positive tumor cells, as well as chymase and VEGF gene expressions, were all markedly increased in the high-grade MEC." (PMID 37175975, 2023). "We have taken into account these molecules also because it has been shown that the upregulation of Gal-3 and PCNA reduces tumor cell lysis by NK cells." (PMID 38201234, 2023). "PCNA‐positive cells occupied 58.4% of the tumor epithelial cells in polyps of the sterile water group and 43.4% in the aspirin‐treated group." (PMID 38072949, 2023). "After nsPEFs ablation, the area of tumor fibrosis and the expression of Ki67, proliferating cell nuclear antigen, and α-smooth muscle actin were decreased." (PMID 36920938, 2023). "Immunohistochemical staining of proliferating cell nuclear antigen (PCNA), which represents cell growth, supported the effect of aspirin on the growth of tumor epithelial cells." (PMID 38072949, 2023). "The expressions of NPAS2, Ki67 and PCNA in tumor tissues of nude mice were tested by immunohistochemistry." (PMID 36978001, 2023). "We then examined the location and expression of Ki67 and PCNA by immunohistochemistry in the tumor tissues of ApcMin/+ mice and ApcMin/+ AhR -/- mice." (PMID 37781044, 2023). "In this case, several significant factors were considered, including tumour grade, depth of invasion, PCNA expression, and staging." (PMID 37685545, 2023). "Based on these results, we performed immunohistochemistry to confirm the expression of PCNA as a proliferation marker in tumor tissues." (PMID 37122692, 2023). "mRNA levels of Ki67 and PCNA in the tumor tissues were reduced by ZQD treatment both at low and high doses." (PMID 37576403, 2023). "Only few PCNA positive cells were observed in the tumor tissues in the S2@PsPCs NPs group in comparison with other groups." (PMID 36678616, 2023). "We found that palbociclib/lenvatinib led to maximal suppression of tumor growth with decreased expression of β-catenin and PCNA." (PMID 37872167, 2023).
tumor (continued). "Lastly, an assessment of the FABPi effects on tumor cells in vivo (e.g. effects on proliferation markers (proliferating cell nuclear antigen or Ki67) or apoptosis) would be reveal in vivo effects of FABPi." (PMID 36880649, 2023). "The levels of expression of the proliferating cell nuclear antigen (PCNA) were also significantly greater in the tumor masses of hyponatremic mice compared to normonatremic mice (p ≤ 0.02 vs. control group)." (PMID 38069002, 2023). "Compared with the common‐used proliferation biomarker, MCM proteins are more sensitive and particular than PCNA and Ki‐67,323 accurately reflecting cell proliferation status and predicting prognostic tumor patient's survival rate." (PMID 36776764, 2023). "Proliferating cell nuclear antigen (PCNA) is closely related to cell DNA synthesis and plays an important role in the initiation of the proliferation of various tumor cells." (PMID 37755128, 2023). "The IHC analysis of tumor tissues for the expression of proliferation marker PCNA also showed a decreased trend in the MK-8937-treated mice, but this difference did not achieve statistical significance (p = 0.100)." (PMID 38201438, 2023). "The critical function of PCNA in promoting cell proliferation has established its frequent use as a marker of tumour proliferation." (PMID 37685545, 2023). "Epithelial cells with higher UVRAG expression showed higher expression of tumor migration-associated genes (HN1, HMGB2, PCNA, and CBX5)." (PMID 37173968, 2023). "In support of the pro-tumor role of LIMD1-AS1, the Ki67 and PCNA staining showed that LIMD1-AS1 knockdown reduced tumor cell proliferation in vivo." (PMID 37385987, 2023). "Two proliferation markers, Ki67 and PCNA, were employed in the Spearman correlation analyses to assess the relationship between BMPs and the proliferation status of tumours." (PMID 37333824, 2023). "In our study, decreased PCNA expression in xenograft tumor tissues was also detected in the xenograft model treated with NVS-ZP7-4, suggesting that NVS-ZP7-4 significantly inhibited proliferation in vivo." (PMID 37479837, 2023). "PCNA is a crucial factor for DNA replication, and emodin can inhibit tumor cell proliferation and invasion through a PCNA-dependent mechanism." (PMID 38062074, 2023). "Protein extraction was performed on the tumor samples obtained from nude mice, followed by western blot analysis to determine the protein expression levels of PCNA and the EMT process." (PMID 38062041, 2023). "Proliferating cell nuclear antigen (PCNA) as a 36 kd highly conserved nuclear protein of DNA polymerase-delta has been identified as a valuable indicator with which to evaluate tumor cell proliferation and cancer development." (PMID 37373429, 2023). "Collectively, these results illustrate that phosphorylation of PCNA at Y211 conveys versatile functions to promote tumor progression through distinct mechanisms." (PMID 35628489, 2022). "Western blot analysis of tumor cell proliferation markers Ki67 and PCNA further confirmed that RGFP-966 effectively inhibited the proliferation of EC cells." (PMID 36230643, 2022). "For example, UV-irradiated ING 1, a tumour suppressor protein, binds tightly to PCNA leading to the commencement of apoptosis." (PMID 36360296, 2022). "Even though the expression of HIF1α and CA9 was the same in these two groups, tumor tissues derived from mice injected with HepG2 cells overexpressing CFHR3 had lower PCNA expression levels." (PMID 35549979, 2022). "It was observed that in the Inotodiol-treated rats, the expression of the proliferating cell nuclear antigen (PCNA), a tumor proliferation marker, decreased." (PMID 36079579, 2022). "PCNA expression is associated with poor 5-year survival, higher WHO grade, and is correlated with tumor stage, differentiation degree, pathological type, and metastasis in a clinical setup." (PMID 36430528, 2022).
tumor (continued). "Another method of tumor escape from NK cell recognition involves NKp44 interactions via its ligands with proliferating cell nuclear antigen (PCNA) and HLA I, which have shown upregulation on cancerous cells." (PMID 35159109, 2022). "ANXA2 expression was also found to be co-localized with cells expressing proliferating cell nuclear antigen (PCNA), a known marker of cell proliferation and tumour aggressiveness." (PMID 35204653, 2022). "In this study, cleaved caspase 3 and PCNA protein expression was upregulated, which confirmed that GM significantly inhibited the proliferation of tumor cells and induced apoptosis of B16F10 cells." (PMID 35875081, 2022). "PCNAP1 acts as a ceRNA to sponge the tumor suppressor miR-154, preventing it from repressing PCNA expression." (PMID 36203765, 2022). "IHC revealed that linc00976 overexpression increased KI67 and PCNA protein expression in excised tumor tissues." (PMID 36400758, 2022). "Antigen markers of migration and cell proliferation, proliferating cell nuclear antigen (PCNA) and E-cadherin, from tumor tissue in the X-PDT group were remarkably different from that of the control group." (PMID 34466749, 2022). "Together, the current results suggest that Y211 phosphorylation in PCNA plays a key role in the crosstalk between cancer cells and stroma to foster a conducive environment for tumor invasion." (PMID 35628489, 2022). "In order to evaluate proliferative tumor potential, two markers, namely, proliferating cell nuclear antigen (PCNA) and Ki-67 were studied in HPV- and EBV-associated malignancies, the results revealing their usefulness in estimating tumor aggressiveness." (PMID 35890003, 2022). "Further, the melittin–dKLA group showed significant decreases in the expression of PCNA compared with the PBS group in tumor tissues." (PMID 35328518, 2022). "After liensinine treatment, the proportion of PCNA positive cells decreased substantially, while the number of cleaved caspase 3 positive cells increased in tumor tissues." (PMID 35116094, 2022). "PCNA is related to tumor growth rate; therefore, PCNA expression is used as an important proliferative marker." (PMID 35814368, 2022). "Compared with those in group T, the number of Ki67-and PCNA-positive cells in tumor tissues of group GT was lower and the Ki67 and PCNA protein expression levels were significantly lower (both P < 0.001)." (PMID 35978996, 2022). "Captopril treatment also had a marked and significant effect on carcinogenesis, as shown by the decrease of gross tumor nodules by 60% (P < 0.01) and by the decrease of proliferating cell nuclear antigen (PCNA) staining used as a marker for cell proliferation." (PMID 35801591, 2022). "We stained tumor sections using anti-PCNA antibodies and found that the sericite group showed lower proliferation (brown) compared to tumor sections from the saline group." (PMID 36199546, 2022). "Hematoxylin and eosin (H&E) staining showed that atypia of the tumor cells from EpiCD147-OE mice, with a 16.45 ~ 26.23% positive PCNA staining rate, indicating cell proliferation." (PMID 35964097, 2022). "While tumors of Vav:Cre-Phd2fl/fl and control mice were equally apoptotic as assessed by CC3 IHC staining, tumors from Vav:Cre-Phd2fl/fl mice showed aggravated tumor proliferation compared with their controls as assessed by IHC for PCNA." (PMID 36509284, 2022). "Similar to what was found for the rag2−/− animal, tumor grafts observed in the irradiated transplant also showed high proliferative capacity as indicated by PCNA immunostaining." (PMID 36230482, 2022).
tumor (continued). "The ‘marker of proliferation Ki-67’ (MKI67) and ‘proliferating cell nuclear antigen’ (PCNA) are clinically important indicators commonly used to assess tumor cell proliferation, as well as the degree of malignancy and prognosis." (PMID 36010686, 2022). "Now, the literature shows that the reliance of tumor cells on BER pathways comprising PCNA makes an attractive target for cancer therapy." (PMID 36430528, 2022). "To further investigate tumor cell proliferation and apoptosis in these tumors, we performed IHC of proliferating cell nuclear antigen (PCNA) and cleaved caspase-3 (CC3)." (PMID 36509284, 2022). "Meanwhile, the combination therapy had a better inhibitory effect on the levels of phosphorylated RB and PCNA in tumor tissues." (PMID 35463335, 2022). "In contrast, MCM6-expressing cells only existed in the isthmus of adjacent non-tumor tissue, a region enrichment of proliferating cells which were PCNA-positive." (PMID 36185598, 2022). "IHC results showed that SCAP-positive tumour cells tended to have higher PCNA expression in the nucleus and showed the lowest proliferation in the Ly + Sora and Sora groups." (PMID 35354475, 2022). "Consistently, the in vivo study showed that tumor size, tumor weight, and proliferating cell nuclear antigen protein expression in tumor tissue are significantly reduced in the high-dose RTP treatment group." (PMID 35269987, 2022). "The results of Western blotting showed that 200 mg/kg NaBu inhibited the expressions of Bcl‐2 and PCNA in the mouse tumour tissues." (PMID 35429101, 2022). "Strikingly, in vivo administration of β-CLA, while reducing the level of Ala to a similar extent as in vitro, largely reduced the tumor burden that was accompanied by reduced mTORC1 and cell proliferation indicated by p-S6, p-4EBP1, and PCNA." (PMID 36256480, 2022). "Compared to the SF8628-control, all investigational preparations significantly reduced the number of PCNA-positive cells in the SF8682 tumor tissue." (PMID 36142368, 2022). "PCNA is a cofactor of DNA polymerase δ, which takes part in DNA replication and has been recognized as a marker to evaluate tumor cell growth." (PMID 35656441, 2022). "Tumor sections were blocked and immunostained with antibodies targeting Ki67 (1:200) or PCNA (1:200)." (PMID 35177075, 2022). "Immunohistochemistry of tumor specimens revealed lower Ki-67 and PCNA expression in the LINC00857 knockdown group compared with the high LINC00857 expression." (PMID 35418193, 2022). "Immunohistochemical analysis for the expression of PCNA in tumor sections derived from Cu-B-treated (ID) animals showed a significant decline in the PCNA expression, which authenticated the ability of Cu-B to inhibit tumor cell proliferation." (PMID 35756619, 2022). "PCNA, a highly conserved nuclear protein of DNA polymerase-delta, has been widely used as a specific marker to evaluate tumor cell proliferation." (PMID 34466749, 2022). "Immunohistochemistry (IHC) results showed a visible decrease in PCNA and Ki-67 expression in xenograft tumor tissues from the NR2F1-AS1-knockdown groups compared with control tumors." (PMID 35283481, 2022). "Further immunohistochemical results indicated that the expression levels of PCNA, the antiapoptotic regulator Bcl2, the migration-related protein vimentin, and the Wnt pathway protein β-catenin were significantly reduced in tumor tissues." (PMID 35348430, 2022). "Compared with those in the C group, the numbers of Ki67-and PCNA-positive cells in tumor tissues of the G, T, and GT groups were lower and the Ki67 and PCNA protein expression levels were significantly lower (all P < 0.001)." (PMID 35978996, 2022). "PCNA is a key protein for abnormal cell proliferation and is closely related to tumor growth, metastasis and prognosis." (PMID 36213440, 2022).
tumor (continued). "Our results showed that L. plantarum-12 oral administration significantly reduced PCNA protein expression, one of cell proliferation and apoptosis markers, indicating that L. plantarum-12 inhibited tumor cell proliferation." (PMID 35565884, 2022). "The results indicated that KI67 and PCNA expression levels were significantly decreased in the tumor tissues." (PMID 35635094, 2022). "Immunohistochemistry (IHC) revealed that linc00976 knockdown triggered a reduction in KI67 and proliferating cell nuclear antigen (PCNA) protein expression in excised tumor tissues." (PMID 36400758, 2022). "At the same time, we also detected Ki67 and PCNA, which were related to tumor proliferation, and the results showed that the protein level of CDKN2A in OS tissues was positively correlated with ki67." (PMID 36263140, 2022). "An additional proliferative cluster, cluster 16, appeared in Bx3 and Bx4, comprised of tumor and stromal cells expressing high levels of Ki67 (31.3×) and/or PCNA (2.4×)." (PMID 35243422, 2022). "Antibodies against PCNA or monoclonal antibody termed Ki-67 can be used for grading different neoplasms." (PMID 35628865, 2022). "The number of PCNA-positive cells in the PBT24-control tumor accounted for 63.8% of the total number of cells, while in the SF8628-control tumor, the number of PCNA-positive cells accounted for 90.8%." (PMID 36142368, 2022). "The expression levels of PCNA and Ki67 in tumor specimens measured by IHC were lower in the laser + PLGA-IR780 NPs group than in the control, laser alone, and two single NP groups, while the laser + MH-PLGA-IR780 NPs group showed the lowest expression." (PMID 35177075, 2022). "Drugs reducing PCNA expression in tumor cells are expected to have a broader anticancer therapeutic spectrum than medicines targeting specific signal proteins." (PMID 35216113, 2022). "Collectively, these results are consistent with a notable role for Y211 phosphorylation in PCNA in maintaining the stemness of cancer cells and tumor invasiveness." (PMID 35628489, 2022). "After removing the tumour, we performed western blotting and immunohistochemical experiments on the tumours of the mice to test the expression of STAT3 and PCNA, which represents tumour proliferation." (PMID 35517401, 2022). "In this study, Ki67 and PCNA were greatly overexpressed in group C as shown by many brown-yellow particles in the nucleus, indicating that the tumor cells were in an active stage and a bad prognosis." (PMID 35978996, 2022). "IHC staining unveiled that overexpression of HAR1A reduced tumor cell proliferation, as shown by decreased MCM2 and PCNA positive tumor cells in lenti-HAR1A cell-derived tumors." (PMID 35740511, 2022). "When accounting for tumour subtype in the Validation cohort, we found significant higher expression of PCNA and Stathmin signatures in young compared to old in the TNBC subtype (P = 0.009 and P = 0.029)." (PMID 35995935, 2022). "In assessing the effect of AOM/DSS on cell proliferation, Ki67, PCNA, BrdU, and Cyclin D1 expression was identified in the colonic crypt cells and tumor epithelia by immunofluorescence staining." (PMID 35269806, 2022). "As confirmed by histological analysis, oral administration of GA for 8 weeks decreases tumor size, damages tumor structure, and lowers expression of HDAC1 and PCNA in tumor mass." (PMID 36233012, 2022). "PCNA exists only in normal proliferating cells and tumor cells, and it has been used as a good indicator for cell proliferation." (PMID 36578555, 2022). "In the cells of the connective tissue that replaced the tumor nodules eliminated after the irradiation and the emerging epithelial regeneration in the basal layer of the epidermis, intensely stained PCNA-positive nuclei were detected." (PMID 35684383, 2022). "Other studies showed that PCNA was up-regulated in tumor, and high PCNA levels related to poor prognosis." (PMID 35164019, 2022).